LMBRD2 (LMBR1 domain containing 2)
Description:
Recruited to ligand-activated beta-2 adrenergic receptor/ADRB2, it negatively regulates the adrenergic receptor signaling pathway. May also regulate other G protein coupled receptors including type-1 angiotensin II receptor/AGTR1 (Probable).
Synonyms: DKFZp434H2226; DENBA
Tractability: Antibody: UniProt places it where antibodies can reach, with high confidence; UniProt predicts a signal peptide or a membrane-spanning region; its Gene Ontology location is reachable by antibodies, with medium confidence. PROTAC: ubiquitination databases record sites on it; its protein half-life has been measured.
Gene: Protein-coding gene on chromosome 5 (36,098,407 to 36,151,921, reverse strand). Ensembl gene ENSG00000164187.
Subcellular location: Cell membrane
Subcellular location (Human Protein Atlas): Cytosol; Nucleoplasm
Gene Ontology:
Biological process: adrenergic receptor signaling pathway
Cellular component: membrane; plasma membrane
Genetic constraint (gnomAD): Loss-of-function variants: 22 observed, 40.64 expected, observed/expected ratio (o/e) 0.54, 90% interval 0.39 to 0.77. The upper end of that interval is the gene's LOEUF score, 0.77, which puts it in group 3 of 6, group 1 being the genes least tolerant of losing a copy. Missense variants: 317 observed, 430.28 expected, observed/expected ratio (o/e) 0.74, 90% interval 0.67 to 0.81. Synonymous variants: 116 observed, 143.84 expected, observed/expected ratio (o/e) 0.81, 90% interval 0.69 to 0.94.
Homologues: Orthologues: chimpanzee LMBRD2 (99% identical), macaque LMBRD2 (99% identical), dog LMBRD2 (96% identical), pig LMBRD2 (96% identical), rat Lmbrd2 (95% identical), mouse Lmbrd2 (95% identical), rabbit LMBRD2 (94% identical), guinea pig LMBRD2 (94% identical), tropical clawed frog lmbrd2 (83% identical), zebrafish lmbrd2b (76% identical), zebrafish lmbrd2a (74% identical), Drosophila melanogaster CG8135 (44% identical), and 1 more.
Diseases named in the same sentence as LMBRD2 in open-access papers:
LMBRD2 is named in the same sentence as 3 diseases in open-access papers, as found by Europe PMC text mining. Sharing a sentence is not in itself a finding about the gene and the disease. The quoted sentences say what the papers report.
Floating-Harbor syndrome (1 paper, 2022). Floating-Harbor syndrome is a genetic developmental disorder characterized by facial dysmorphism, short stature with delayed bone age, and expressive language delay. "Examples of reclassification of VUS in our study include a novel and distinctive phenotype for the SRCAP gene, previously associated with Floating-Harbor syndrome only, a VUS in PRPS1 recently also reported by others, and small genotype-phenotype case series for LMBRD2 and PAX3." (PMID 35710456, 2022).
leukemia (1 paper, 2016). A malignant (clonal) hematologic disorder, involving hematopoietic stem cells and characterized by the presence of primitive or atypical myeloid or lymphoid cells in the bone marrow and the blood. "LMBRD2 encodes LMBR1 domain‐containing protein 2, which has not been reported any association with leukemia." (PMID 26711002, 2016).
LMBRD2 also shares sentences with these, for which no sentence is quoted: metabolic disease (1 paper).